BRCA2 (BRCA2 DNA repair associated)
Diseases named in the same sentence as BRCA2 in open-access papers (continued):
Sharing a sentence is not in itself a finding about the gene and the disease.
ovarian carcinoma (continued). "BRCA1 and BRCA2 are tumor suppressor genes located on chromosome 17q21 and 13q12, respectively, and are responsible for an increased risk of breast and ovarian cancer development." (PMID 38792636, 2024). "Clinical management of Asian BRCA1 and BRCA2 pathogenic variants (PV) carriers remains challenging due to imprecise age-specific breast (BC) and ovarian cancer (OC) risks estimates." (PMID 38333895, 2024). "The key HR genes, BRCA1 and BRCA2, are particularly significant as their germline pathogenic variants are associated with a hereditary predisposition to breast and/or ovarian cancer." (PMID 39080120, 2024). "Women with BRCA2 pathogenic variants had a corresponding risk of 55% (95% CI, 41%-70%) and 16.5% (95% CI, 7.5%-34%) for breast and ovarian cancers, respectively." (PMID 39507757, 2024). "Within the 2022 ELN AML diagnostic criteria, in the separate “AML with germline predisposition” category, it is highlighted that the BRCA1 and BRCA2 inherited mutations predispose not only to myeloid neoplasms but also to BC and ovarian cancers." (PMID 38398301, 2024). "Beyond established genetic mutations like BRCA1 and BRCA2, researchers are exploring the contribution of other genetic alterations and environmental factors to ovarian cancer risk." (PMID 38084173, 2023). "One study reported that relatives of BRCA1 and BRCA2 carriers have an increased risk for breast and ovarian cancers, and relatives of BRCA2 carriers also have an increased risk for pancreatic cancer." (PMID 36861435, 2023). "Unlike most BRCA2 truncating variants that confer a high risk of breast and ovarian cancers, the BRCA2 p.K3326* mutation is regarded as a low-penetrant susceptibility allele for these hormone-related cancers." (PMID 37943872, 2023). "JQ1 has been shown to re-sensitize BRCA2-mutated ovarian cancer cells that have developed resistance to olaparib." (PMID 37735513, 2023). "Several mutations in the BRCA1/BRCA2 genes are known to increase the risk of developing ovarian cancer." (PMID 36981032, 2023). "To conclude, although mosaicism for BRCA1 and BRCA2 variants seems to be rare, low-level mosaic mutations can contribute to the aetiology of breast and ovarian cancer susceptibility." (PMID 36833429, 2023). "Heterozygous germline mutation in the BRCA1 gene confers a 60% lifetime risk of breast or ovarian cancer, whereas BRCA2 mutations are associated with a risk of breast or ovarian cancer of 55% and 15%, respectively." (PMID 37415740, 2023). "For example, germline mutations in BRCA1 and BRCA2 tumor suppressor genes increase the risk of breast and ovarian cancer in humans, and Brca1 and Brca2 genes participate in the embryonic development and differentiation of mammary glands in mice." (PMID 37239953, 2023). "Currently, we know that defective homologous recombination DNA repair imposed by BRCA1 or BRCA2 deficiency sensitizes cells to and is currently used in the treatment of ovarian cancer." (PMID 37686547, 2023). "A recent review pointed out the predominance of deleterious variants in breast and ovarian cancer genes among PanC patients, with BRCA2 and ATM having the highest prevalence of pathogenic mutations in both sporadic and unselected PanC." (PMID 36717774, 2023). "Strong family history of breast and ovarian cancer indicates high likelihood of germline BRCA1 or BRCA2 pathogenic variant." (PMID 37173335, 2023). "Taken together, the data provide evidence that MRE11 blockade or depletion is associated with selective toxicity in BRCA2-deficient ovarian cancer cells." (PMID 37446144, 2023). "More specifically, women having mutations in BRCA1 and BRCA2 are thought to have elevated risk for the development of ovarian cancer." (PMID 36903316, 2023).
ovarian carcinoma (continued). "Similar to BRCA1, a secondary mutation in BRCA2 has also been shown to restore the mutant BRCA2 reading frame into the wild-type reading frame in cisplatin-resistant ovarian cancer." (PMID 37110218, 2023). "The search for “BRCA3” has led to the conclusion that no gene with a similar population frequency of pathogenic variants and associated breast and ovarian cancer risk as BRCA1 or BRCA2 exists." (PMID 37563628, 2023). "Pathogenic variants in BRCA2 are known to significantly increase the lifetime risk of developing breast and ovarian cancers." (PMID 37980415, 2023). "Since the efficacy of these screening approaches is still unclear, prophylactic ovarian surgery is an essential option for patients with confirmed BRCA1 or BRCA2 mutations or a strong family history of breast and/or ovarian cancer." (PMID 37370973, 2023). "BRCA1 or BRCA2 mutation carriers show a lifetime risk of up to approximately 85% and 20%–40% for breast and ovarian cancers, respectively." (PMID 37644384, 2023). "Breast cancer genes 1 and 2 (BRCA1 and BRCA2) are tumor suppressor genes, and mutations in either strongly increase the risk of the carrier towards developing breast and ovarian cancer." (PMID 37108225, 2023). "While the association of BRCA1 and BRCA2 PV with breast and ovarian cancer risks is well-defined, the potential association of these variants with other cancers is not so well established." (PMID 38067403, 2023). "Carrying germline pathogenic variants in BRCA1 or BRCA2 (gBRCA) confer a high risk for developing breast or ovarian cancer throughout a patient’s life." (PMID 37119509, 2023). "The Manchester score is based on family history and pathological characteristics of the tumor and indicative of the risk of a germline BRCA1 or BRCA2 mutation for patients with breast or ovarian cancer." (PMID 36112334, 2023). "BRCA1 and BRCA2 play a central role in DNA repair and their germline pathogenic variants (gBRCA) confer a high risk for developing breast and ovarian cancer." (PMID 37119509, 2023). "For example, one study showed that ATR inhibitor in combination with olaparib promoted greater activity than did olaparib monotherapy via mitotic catastrophe-induced cell death in BRCA2-mutated ovarian cancer." (PMID 38069409, 2023). "The chance of developing breast and ovarian cancers is considerably increased by inheriting a deleterious mutation in either the BRCA1 or BRCA2 gene." (PMID 37886170, 2023). "The BRCA1 and BRCA2 tumor suppressor genes are critical for the HRR of DNA double‐strand breaks by the HRR pathway; therefore, BRCA1/BRCA2‐mutated ovarian cancers are usually more sensitive to cisplatin." (PMID 37229486, 2023). "Patients with germline BRCA1 or BRCA2 mutations account for about only 15% of all patients with ovarian cancer, but approximately 50% of epithelial ovarian cancers harbor defects in HRR." (PMID 37457127, 2023). "Women carrying deleterious BRCA2 germline mutations have a lifetime risk of up to 27% of developing ovarian cancers." (PMID 37446144, 2023). "As a result, managing the risk of ovarian cancer is critical for women who have a PV in BRCA1 or BRCA2." (PMID 37602539, 2023). "The risk for ovarian cancer in female relatives of BRCA1 carriers is even higher than female relatives of BRCA2 carriers." (PMID 36861435, 2023). "In summary, these findings do not support a strong association between early-life physical activity and ovarian cancer among women with a BRCA1 or BRCA2 mutation." (PMID 38019076, 2023). "PARP inhibitors (PARPi) were first approved for the treatment of breast and ovarian cancers with defects in the HR pathway due to BRCA1 or BRCA2 mutations." (PMID 36672401, 2023). "Approximately 10–15% of patients with epithelial ovarian cancer have an inherited (germline) BRCA1 or BRCA2 mutation." (PMID 38201604, 2023).
ovarian carcinoma (continued). "The cumulative risk of developing ovarian cancer has been reported as 39–44% for BRCA1 mutations and 11–17% for BRCA2 mutations, compared to a cumulative risk of ovarian cancer in the general population of 1–2%." (PMID 37957733, 2023). "Women who carry mutations of BRCA 1 and BRCA2 genes have an augmented risk of breast and ovarian cancer and a markedly augmented probability of dying because of cancer compared to the general population." (PMID 36614207, 2023). "BRCA1 and BRCA2 mutations are responsible for most hereditary epithelial ovarian cancer, while Lynch syndrome is associated with clear-cell and endometrioid tumors." (PMID 36984544, 2023). "The genetic predispositions of defective BRCA1 and/or BRCA2 (the second most common mutations in ovarian cancer) genes are responsible for only 10–20% of all ovarian cancer cases, with the genetic marker increasing a patient’s risk by 15–60%." (PMID 36671544, 2023). "In BRCA1 mutation carriers, oral contraception lowered the risk of ovarian cancer by 45–50%, and in BRCA2 mutation carriers, it decreased the risk by 60%." (PMID 36835955, 2023). "Risk-reducing bilateral salpingo-oophorectomy (RRSO) is an effective prophylactic surgery provided to premenopausal women carrying BRCA1 or BRCA2 mutations and presenting an increased risk of developing breast or ovarian cancer." (PMID 36826146, 2023). "It has been shown that around 10–15% of epithelial ovarian cancer (EOC) patients carry germline mutation in BRCA1 or BRCA2 with the highest incidence seen with HGSE subtypes." (PMID 37181681, 2023). "BRCA2 is a tumor suppressor gene that is commonly implicated in breast and ovarian cancers but has also been associated with poor prognosis in gliomas." (PMID 37686092, 2023). "Similar findings have previously been reported showing that pathogenic BRCA2 variant carriers were diagnosed with pancreatic cancer at an older age compared to breast or ovarian cancer patients." (PMID 37951914, 2023). "Some mutations in BRCA2 are associated with increased risk of breast and ovarian cancer as well as other cancers such as pancreatic and prostate cancer." (PMID 37980415, 2023). "BRCA1-mutated patients have a lifetime risk of developing BC of 65% and an ovarian cancer risk of 39%, while the risk of BC is 45% and the risk of ovarian cancer is 17% in BRCA2-mutated patients." (PMID 37109459, 2023). "Women with BRCA1 or BRCA2 gene mutations are at increased risk of breast and ovarian cancer and often undergo operations to remove both their ovaries in order to prevent ovarian cancer." (PMID 36900415, 2023). "Epidemiological studies show that women with deleterious germline mutations in BRCA1 or BRCA2 gene have a higher lifetime risk of ovarian cancer." (PMID 37386498, 2023). "We then proceeded to evaluate potential mechanisms of resistance to MRE11 blockade in BRCA2-deficient ovarian cancer cells." (PMID 37446144, 2023). "BRCA1 and BRCA2 genes are recognized as the primary inherited causes of breast and ovarian cancer since they were discovered in 1990s." (PMID 38274092, 2023). "Ovarian cancer histological subtypes were assessed for their potential utility in future prediction of germline BRCA1 or BRCA2 variant pathogenicity." (PMID 37076566, 2023). "Although pharmacological ablation is widely believed to be at least as effective as surgical ablation, surgery is primarily used in a risk-reduction setting for women with an increased risk of both breast and ovarian cancer due to BRCA1 or BRCA2 mutations." (PMID 36835955, 2023). "Breast cancer susceptibility gene 1/2 (BRCA1/BRCA2) mutations predispose patients to select cancers, especially breast and ovarian cancer." (PMID 37274233, 2023). "Female relatives of BRCA1 and BRCA2 carriers are at increased risk for breast and ovarian cancers, and male relatives of BRCA2 carriers are at increased risk for pancreatic and prostate cancers." (PMID 36861435, 2023).
ovarian carcinoma (continued). "Family 7 harbor a pathogenic BRCA2 mutation c.2808_2811del causing hereditary breast and ovarian cancer." (PMID 37296477, 2023). "There are few studies reporting the association of BRCA2 mutations with immune biomarkers in tumors such as gastroesophageal cancers or with an immunogenic microenvironment in ovarian cancers." (PMID 37813891, 2023). "Clinically, BRCA mutations have been simply regarded as HR defects, and BRCA1- and BRCA2-mutated ovarian cancers have been treated as the same disease." (PMID 38017453, 2023). "The identification of BRCA1 and BRCA2 pathogenic variants is recommended as an effort of primary prevention for epithelial ovarian cancer." (PMID 37143950, 2023). "Population-based studies have shown that BRCA1 and BRCA2 mutations are found in roughly 15% of all ovarian cancer cases." (PMID 37228496, 2023). "Specific genetic tests on BRCA1/BRCA2 status are available and work well for ovarian cancer, but only a small fraction (about 10%) of ovarian cancers are associated with those variants." (PMID 36981032, 2023). "BRCA2 mutated ovarian cancer cells that resist platinum chemotherapy revealed yet another mechanism that involves R-loop interacting proteins." (PMID 37108225, 2023). "Breast cancer genes 1 and 2 (BRCA1, BRCA2) are two tumor suppressor genes that strongly impact a women’s overall risk of developing breast and ovarian cancer." (PMID 37228496, 2023). "Women with a pathogenic or likely pathogenic variant (PV) in BRCA1 or BRCA2 have high lifetime risks of developing ovarian cancer." (PMID 37602539, 2023). "Pathogenic variants (PVs) in BRCA1 and BRCA2 increase the lifetime risks of breast and ovarian cancer." (PMID 37887578, 2023). "A loss of function mutations in the BRCA1 and BRCA2 genes is associated with a higher likelihood of the development of breast and ovarian cancers." (PMID 37366887, 2023). "International guidelines recommend RRSO after completion of childbearing or at 35–40 years of age for BRCA1 mutations carriers or at 40–55 years of age for BRCA2 mutation carriers to reduce the risk of breast and ovarian cancers." (PMID 36614207, 2023). "Women who carry an inherited deleterious mutation in the BRCA1 or BRCA2 gene face the highest risk of developing ovarian cancer." (PMID 38136256, 2023). "For carriers of BRCA1 mutations, the risk of developing breast and ovarian cancer by age of 80 years is estimated to be 72% and 44% respectively, while it is 69% and 17% respectively for BRCA2 carriers." (PMID 38274092, 2023). "It is well-known that BRCA1 and BRCA2 carriers are at increased risk for breast and ovarian cancers, and BRCA2 carriers are at increased risk for pancreatic and prostate cancers." (PMID 36861435, 2023). "Here, we show that effecting an MRE11 blockade using a prototypical inhibitor (Mirin) induces synthetic lethality (SL) in BRCA2-deficient ovarian cancer cells, HeLa cells, and 3D spheroids compared to BRCA2-proficient controls." (PMID 37446144, 2023). "This appeared to be due to later ovarian cancer onset in carriers of BRCA2 mutations compared with their BRCA1 counterparts, after childbearing age." (PMID 37664647, 2023). "Five models predicted biallelic loss of BRCA2 in cancers of the ovary, prostate, pancreas, and breast." (PMID 36883553, 2023). "Many studies demonstrated that germline and somatic BRCA1 and/or BRCA2 mutations are related to a better prognosis in ovarian cancer patients." (PMID 35267543, 2022).
ovarian carcinoma (continued). "BRCA1 and BRCA2 are the most studied BC susceptibility genes that explain a significant proportion of both hereditary breast and ovarian cancers." (PMID 36553480, 2022). "When to discuss risk-reducing mastectomy in BRCA1/BRCA2 carriers after a diagnosis of advanced stage ovarian cancer can be a challenging area in providing patient-centred genetic counselling." (PMID 36068545, 2022). "The c.5266dupC, c.5177_5180delGAAA, and c.5251C > T variants in BRCA1 and the c.2808_2811delACAA and c.1138delA variants in BRCA2 were the most common variants among breast and ovarian cancer patients from Brazil." (PMID 35918668, 2022). "These DSBs can be repaired in normal cells with proficient HRR; however, DSBs cannot be efficiently repaired in BRCA1- or BRCA2-mutated breast and ovarian cancer cells due to HRR deficiency (HRD)." (PMID 35328658, 2022). "As shown by studies of 200 Polish families with strong aggregation of breast/ovarian cancers, constitutional mutations of the BRCA2 gene are rare in this group, with a frequency of about 4%." (PMID 35395863, 2022). "Carriers of germline mutations in BRCA1 and BRCA2 genes have a lifetime risk of ovarian cancer of 35–60% and 12–25%, respectively, along with an increased risk of peritoneal and fallopian tube malignancies." (PMID 35805770, 2022). "Accordingly, the ALDH1A1 inhibitor NCT-501 synergized with Olaparib in cell culture and xenograft models of BRCA2-mutated ovarian cancer." (PMID 35205643, 2022). "FEN1 inhibition was assessed in ovarian cancer cell lines and was demonstrated to potentiate cisplatin cytotoxicity as well as being synthetically lethal to BRCA2-deficient cells." (PMID 36420962, 2022). "This was the first study in Vietnam to investigate mutations of BRCA1 and BRCA2 genes in breast and ovarian cancer patients with the criteria of HBOC syndrome, and to develop a risk score associated with the cohort based on carrier status and family history." (PMID 35205313, 2022). "Using BRCA1/BRCA2 mutated breast and ovarian cancer as the control, we observed that BRCAness is widely present in multiple cancer types." (PMID 36497135, 2022). "Pathogenic variants of BRCA1 and BRCA2 only explain the genetic cause of approximately 10% of hereditary breast and ovarian cancers (transmitted to offspring), underscoring the clinical importance of testing other DNA repair genes." (PMID 35785170, 2022). "Monoallelic and biallelic mutations in BRCA2 cause hereditary breast and ovarian cancer and Fanconi anaemia (FA), respectively." (PMID 35053516, 2022). "Relatively little is known about reproductive decision-making in women harboring mutations in the BRCA1 and/or BRCA2—pathogenic variants that confer different cancer risk profiles and underlie hereditary breast and ovarian cancer." (PMID 35326645, 2022). "A BSO is performed between the ages of 35 and 40 in BRCA1 carriers and 40 and 45 in BRCA2 carriers due to the late onset and can reduce the risk of ovarian cancer by 96%." (PMID 35805770, 2022). "The HR mechanism is usually associated with cancer and BRCA1 and BRCA2 mutations, which are linked to hereditary breast and ovarian cancer." (PMID 36499000, 2022). "Women with inherited pathogenic variants in the BRCA1 and BRCA2 genes have a high risk of developing both breast and ovarian cancer." (PMID 35123550, 2022). "Standard guidelines identified germline mutations in BRCA1 and BRCA2 genes in 15% of women affected with ovarian cancer, whereas somatic mutations in an additional 7%." (PMID 36010253, 2022). "The most prevalent BRCA2 mutation in ovarian cancer patients was c.9371A>T (six patients) (35%), followed by c.6839_6840insA (two patients)." (PMID 35409996, 2022). "This Portuguese BRCA2 founder mutation is present in ~30% of all Portuguese families with hereditary breast and ovarian cancer, representing 55% of all BRCA2 germinal mutation carriers in Portugal." (PMID 35203410, 2022).